HIF1A (hypoxia inducible factor 1 subunit alpha)
Diseases named in the same sentence as HIF1A in open-access papers (continued):
Sharing a sentence is not in itself a finding about the gene and the disease.
tumor (continued). "Research has demonstrated that activation of the mTOR pathway increases the expression of HIF-1α and c-Myc, further upregulating glucose transporter 1 (GLUT1), glycolysis-related enzymes, LDHA, MCT1, and MCT4, thereby promoting lactate production in tumor cells." (PMID 40034817, 2025). "Notably, ROS-mediated stabilization of HIF-1α drives angiogenesis and EMT in hypoxic tumors, but recent studies suggest that HIF-1α can also induce antioxidant responses, mitigating ROS and promoting tumor survival." (PMID 40801639, 2025). "Importantly, IL-18 is necessary to activate NF-κB and boost the antitumor activity associated with HIF-1α; in its absence, NK cells lacking HIF-1α cannot effectively control tumor progression." (PMID 40297580, 2025). "In addition, there are angiogenesis‐related markers, including ANGPT1, CD40LG, HIF1A, CCL5, and GPR87, which could contribute to tumour vascularisation." (PMID 40754672, 2025). "Tarceva alone could inhibit tumor HIF-1α protein expression but with no change in regard to the HIF-2α expression." (PMID 39273055, 2024). "The role of HIF-1α in the tumor-promoting effect of PDLIM2 knockdown had not been reported." (PMID 38880883, 2024). "Firstly, it may promote cancer cell proliferation through the activation of HIF1α, which leads to STIM1 puncta formation and SOCE activation, Secondly, it could activate mitochondrial autophagy, depending on the heterogeneity of the tumor." (PMID 39104527, 2024). "HIF-1α-PDGF-VEGF represents a multifaceted network that drives tumor angiogenesis; therefore, the simultaneous targeting of VEGF and PDGF could offer more effective and comprehensive approaches to combat tumor progression." (PMID 38542288, 2024). "Our study aims to specifically identify HIF-1A targeted genes and activated pathways in HCC using computational approaches and to validate the obtained data using HCC organoids, which can be considered a reliable in vitro model to study the role of HIF-1A in the tumor microenvironment." (PMID 39567394, 2024). "Thus, we speculate that through the regulation of HIF1a by IDH1, tumor cells with high IDH1 expression are more sensitive to Scu, and the inhibitory effect of Scu is more significant under hypoxia." (PMID 38622131, 2024). "In addition, the colocalization of IL21-AS1, HIF-1α, and CD24 in necrotic tumour regions further confirmed this hypothesis." (PMID 38702326, 2024). "Interestingly, HIF-1α-positive staining (brown) of tumor tissue was hardly observed in the HIL@Z/P/H+Red+NIR group, which was mainly attributed to the O2 supplement to the tumor by PCC 7942." (PMID 38280861, 2024). "The deletion of HIF-1α in OT-1 CD8 T cells did not exert any significant impact on tumor growth, which may be attributed to the observed ineffectiveness of WT OT-1 CD8 T cells in this context." (PMID 39242595, 2024). "Similar to other oncogenes, HIF-1α increases HIF-1α stimulates SLC7A11 expression, facilitating the exchange of glutamine with cystine, elevating glutathione levels within tumor cells, preventing the accumulation of ROS within tumor cells and impeding the occurrence of ferroptosis in tumor cells." (PMID 38172980, 2024). "The expression of Twist1 in tumor cells is modulated by several regulators including signal transducer and activator of transcription 3 (STAT3), nuclear factor kappa B (NF-κB), steroid receptor co-activator 1 (SRC1), Msh homeobox protein (MSX2), and Hypoxia-inducible factor 1-alpha (HIF-1α)." (PMID 38791037, 2024). "Hepatocyte‐derived HIF1A was gradually activated during the progression of NAFLD disease to adapt to the hypoxic microenvironment and hepatocytes under hypoxic environment led to changes in the metabolism, proliferation and angiogenesis, promoting the occurrence of tumours." (PMID 37994257, 2024).
tumor (continued). "myCAFs are located in CAFs adjacent to tumor cells, while iCAFs marked by PDPN and/or COL14A1 are distant from tumor cells, where hypoxic and acidic environments being located in iCAFs putatively due to poor blood supply is consistent with HIF1A and GPR68 expressions." (PMID 38892190, 2024). "However, some studies suggest that high concentrations of sevoflurane may inhibit tumor invasion by downregulating the p-38 MAPK pathway, reducing HIF-1α activation and suppressing MMP-2/-9 activity." (PMID 39766169, 2024). "But rather than emphasizing the HDACi’s inhibitory effect on HIF-1α, the main mechanism of this combination is the increased production of tumor suppressors such as interferon-γ inducible protein 16 (IFI16) via up-regulating H3K27ac and down-regulating H3K27me3 levels." (PMID 38911968, 2024). "Notably, the interaction of the PH domain with these proteins promotes the degradation of HIF-1α independent of the oxygen concentration and suppresses tumor progression, suggesting a novel function of the PLD-PH domain as a therapeutic target against cancer." (PMID 38945955, 2024). "Preliminary studies in mouse tumor models have also indicated that OMX is long-lasting in circulation and tumors, and it penetrates deep into tumor tissue reducing hypoxia and altering the hypoxic phenotype by downregulating the hypoxia-inducible factor 1 alpha (HIF-1α) pathway." (PMID 38741109, 2024). "Furthermore, chronic inflammation and oxidative stress contribute to the creation of a hypoxic tumour environment, which activates signalling pathways like MAPK/ERK and stabilises hypoxia-inducible factor-1 alpha (HIF-1α), further upregulating the expression of angiogenic factors." (PMID 39683144, 2024). "While the benefit of postoperative radiotherapy was shown in both HIF-1α-positive and negative cancers, more recurrences were recorded among patients with HIF-1α-positive primary tumours, this status also being associated with a higher risk of cancer-related deaths (HR = 1.9 [1.2–2.9], p = 0.004)." (PMID 38920676, 2024). "To elucidate the potential regulatory role of B7-H3 in modulating HIF-1α expression through the PI3K/Akt/mTOR signaling pathway and its impact on downstream glycolysis-related proteins, we conducted immunofluorescence staining on tumor tissues collected from xenograft mouse models." (PMID 38577598, 2024). "Our results demonstrated a significant inhibitory effect of ISO on genes involved in HIF1α signaling and the glycolysis pathway, suggesting that ISO treatment may reverse the metabolic reprogramming in cancer cells and lead to impaired tumor growth and progression." (PMID 38339062, 2024). "Additionally, chronic inflammatory environments can also activate signaling pathways such as nuclear factor kappa B (NF-kB), signal transducer and activator of transcription 3 (STAT3), and hypoxia-inducible factor 1-alpha (HIF-1α) which promote cell survival and proliferation in tumour cells." (PMID 39516433, 2024). "HIF-1α impedes immune surveillance and natural killer (NK) cell infiltration by interfering with MHC class I polypeptide-related sequence A (MICA) and inhibiting the expression of natural cytotoxic receptors and the activator NKG2D, thereby interrupting tumor antigen recognition." (PMID 38891772, 2024). "Accuracy in the measurement of tumor HIF-1α may help to better distinguish responders from non-responders." (PMID 38799423, 2024). "Finally, therapeutic targeting of hypoxia through treatment with terazapamine and FM19G11 (a small molecule inhibitor of HIF-1α and HIF-2α) resulted in a marked reduction of tumor growth and a corresponding decrease in TSD+ CSCs and CTCs and the presence of R-CSCs within the BM." (PMID 39963656, 2024).
tumor (continued). "Among these, HIF-1α is the most well known and mediates the most adaptive changes in response to hypoxic environments in different organs while HIF-2α is considered to have a role in angiogenesis, lipid metabolism regulation, cell migration, and tumor invasion." (PMID 38790642, 2024). "Given that HIF-1α in TAMs is upregulated upon exposure to the TME19,20, it is necessary to evaluate the impact of glutamine-derived aspartate on the HIF-1α level in TAMs, as well as the mechanism by which aspartate metabolism engenders the tumor-promoting capacity of TAMs." (PMID 38689086, 2024). "Therefore, YC-1, a HIF-1α inhibitor, may enhance the antitumor effects of BNCT by increasing boron concentrations, even in hypoxic tumor cells." (PMID 39123497, 2024). "A hypoxic microenvironment promotes binding of HIF‐1α complex is demonstrated to the ALCAM promoter therefore increasing its expression in macrophages, and the ALCAMhigh macrophages co‐localize with exhausted CD8+ T cells in the tumor spatial microenvironment and promote T cell exhaustion." (PMID 38956900, 2024). "The HIF-1 inhibitory activity of furospongolide is mediated through the suppression of tumor cell respiration via the blockade of NADH-ubiquinone oxidoreductase (complex I)-mediated mitochondrial electron transfer, consequently blocking the HIF-1 transcription regulator protein HIF-1α." (PMID 38667760, 2024). "Additionally, there was a significant correlation between nuclear HIF-2α expression and tumor size (P = 0.035), whereas not with HIF-1α (P = 0.106) and HIF-3α (P = 0.701)." (PMID 38571885, 2024). "Recently, it has also been shown that, in A2780 ovarian cancer cells, in turn, HIF-1α promotes the production of ROS mediated by NOX4 via an alternative splicing mechanism, emphasizing how this positive feedback process is involved in cancer angiogenesis and tumor progression." (PMID 39334716, 2024). "In the human PDAC patient tumor transcriptome (TCGA), we identify strong and significant correlations between tumoral GHR expression and known lymphangiogenic (LYVE1, FLT4, VEGFC, and PDPN) and angiogenic (PDGFRa, FGFR1, TGFB3, TGFB1, TGFBR2, HIF1a, IL6, and IL1B) markers." (PMID 39000545, 2024). "Notably, rapid tumor proliferation often leads to insufficient vascularization and subsequent hypoxia, triggering the secretion of angiogenic factors like vascular endothelial growth factor (VEGF) and hypoxia-inducible factor 1-alpha (HIF-1α)." (PMID 38791916, 2024). "PlGF expression is suppressed in trophoblasts under hypoxic conditions induced by shallow placentation; however, the expression is upregulated by hypoxia or overexpressed HIF-1α in nontrophoblast cells, such as endothelial cells, cardiac fibroblasts, and some tumor cells." (PMID 38825645, 2024). "Furthermore, the hypoxic microenvironment can attract lymphoid immune cells, but activated HIF-1α may reduce and deactivate cytotoxic lymphocytes, including NK cells and CD8+ T lymphocytes, thereby inhibiting their anti-tumor efficacy." (PMID 39728157, 2024). "Hence, tumor hypoxia, through the lack of inhibition/degradation of hypoxia-inducible factor 1α (HIF-1α) and its consequent activation, is recognized as the main cause responsible for producing pro-angiogenic factors." (PMID 38791608, 2024). "This crosstalk between HIF-1α and YAP underscores the complexity of cellular responses to hypoxia and suggests potential targets for therapeutic intervention in diseases such as cancer, where hypoxia and dysregulated Hippo signaling contribute to tumor progression." (PMID 39272887, 2024).
tumor (continued). "Furthermore, we elucidated that the repression of miR-598-3p in tumor microenvironment is not dependent on HIF1α." (PMID 38491378, 2024). "Furthermore, HIF-1α binds to the promoter region of VEGF, followed by enhanced tumor angiogenesis." (PMID 36845131, 2023). "Additionally, hypoxia-inducible transcription factor 1α (HIF-1α) could bind with the promoter of HK2 and promote its transcription to increase glycolytic flux for promoting tumor survival and growth." (PMID 37854321, 2023). "When examined in detail, the expression of all hypoxia markers and vessel density were significantly different in pT1b compared with those in non‐neoplasia, whereas the expression of HIF‐1α was not significantly different in pTis‐T1a compared with that in non‐neoplasia, which is a novel finding." (PMID 37329213, 2023). "Our transcriptomic analysis of neutrophils from bone marrow, blood and tumors of OT mice found an up-regulation of glycolytic factors and HIF-1α expression specifically in tumor-infiltrating neutrophils and not neutrophils from the bone marrow or blood of the same mouse." (PMID 36614196, 2023). "Additionally, hypoxia significantly enhanced HIF-1α and ALKBH5 expression in tumor cells." (PMID 36632222, 2023). "In the later stage of treatment, high dosages of sorafenib could continuously induce the downregulation of IL-6 expression and the upregulation of HIF-1α expression, thereby continuing to downregulate the expression of PFKFB3 and inhibiting tumor growth and invasiveness." (PMID 37476196, 2023). "10/24 hypoxia genes were significantly upregulated in HIF-1α-positive versus -negative tumours." (PMID 37085598, 2023). "However, TEPP-46 treatment did not alter the expression of HIF-1α and PKM2, the level of glycolytic activity, or the induction of type I IFN in tumor-infiltrating STING-deficient DCs." (PMID 36821379, 2023). "Also presented are the findings about the impact of a hypoxia mimetic (CoCl2) and of an activator of the AhR signaling pathway (B[a]P) on mRNA levels of HIF-1α, AhR, and of their target genes in primary culture of patient-derived nonembolized tumor cells." (PMID 37305351, 2023). "By the use of lactate as the anabolic fuel source, activation of mTORC1/ HIF-1α in a metastatic-cancers-driven TME has been demonstrated to switch cell lactate metabolism toward increased production of protein, lipids, and nucleotides for tumor biomass expansion and cancer proliferation." (PMID 36986244, 2023). "Subsequent qPCR with reverse transcription (qRT–PCR) examination validated the significant suppression for Vhl expression, while no significant alteration for Hif1α level was observed in eWAT and iWAT from 231/Ctrl mice when compared to tumour free mice or 231/Rab27a KD mice." (PMID 37620316, 2023). "Moreover, another study highlighted that conditional deletion of HIF-1α in NK cells reduces tumour progression by inducing non-productive angiogenesis in tumours." (PMID 36797782, 2023). "Propofol decreased hypoxia inducible factor 1α (HIF1α), interleukin 1β (IL1β), and hepatocyte growth factor (HGF) gene expressions and increased tissue inhibitor of metalloproteinases 2 (TIMP-2) gene and protein expression in comparison to sevoflurane in the tumour tissue." (PMID 35953652, 2023). "Hypoxia-inducible factor 1-alpha (HIF-1α) may indirectly stabilize and activate the transcription of numerous genes involved in copper metabolism, including those controlling CTR1, thereby contributing to higher copper levels in tumor cells." (PMID 37427098, 2023). "Therefore, copper can affect the activity of LOX and LOXL enzymes, the expression of MEMO1, and the binding of HIF-1α to target genes with HRE sequences (hypoxia response elements), thereby regulating the expression of EMT-related genes and promoting tumor cell metastasis." (PMID 37427098, 2023).
tumor (continued). "Therefore, due to the collection of literature contrary to the downregulation of HIF1α in PCa metastasis and its potential role as a tumour suppressor, we do not consider HIF1α a promising AR-V7 target gene." (PMID 36937454, 2023). "Moreover, ROS’ intracellular accumulation results in the stabilization and activation of HIF-1α and the degradation of SIRT3, leading to the transcription of VEGF, LDHA and PDK1, even under normoxic conditions, promoting in such a way tumor angiogenesis and progression in GC." (PMID 37371466, 2023). "Although we do not discuss the relationship between YAP1 and glycolysis in detail here, our findings and recent studies suggest that YAP1 promotes the transcription of HIF1A in cancer, indicating that LPA could affect tumor glycolysis through multiple upstream pathways." (PMID 37990271, 2023). "Moreover, tumor cells are frequently under conditions of oxygen and nutritional deprivation, which leads to autophagy activation via PKC-augmented JNK activation, hypoxia-induced factor-1 α (HIF-1α), AMPK activation, and mTOR inactivation, respectively." (PMID 36833401, 2023). "In addition, Nile red staining showed that SKA3 overexpression increased triglyceride levels in tumours, which could be reversed by PARP1 and HIF-1a knockdown." (PMID 37821935, 2023). "Indeed, activated HIF1α signaling in fibroblasts was found to determine the volume and mass of the tumor without a significant increase in tumor angiogenesis." (PMID 38234683, 2023). "HIF-1α and NRF2 have distinct and overlapping roles in the cellular response to hypoxia, and emerging evidence suggests that coordinated signaling through NRF2 and HIF-1α is critical for tumor survival and progression and that the ALDH family is one of the coordinating signals." (PMID 37730658, 2023). "Interestingly, it was shown that tumor MDSCs exposed to hypoxia upregulate the expression of inos and argI via HIF-1α, thus acquiring the ability to suppress antigen-nonspecific T-cell functions and focus on the immune suppression they drive in TME." (PMID 37895302, 2023). "Thus, we hypothesised that hypoxia-induced enhanced HIF-1α secretion also stimulated ALKBH5 expression and accelerated early lymphangiogenesis in EOC cells, thereby enhancing tumor metastasis." (PMID 36632222, 2023). "Unlike propofol, sevoflurane exposure resulted in bigger tumour size, shorter survival time (assessed with the clinical endpoints, including body weight loss > 20% and tumour volume > 70 mm3), higher HGF, HIF1α, IL1β and TNFα expressions, and lower E-cadherin and TIMP-2 expressions." (PMID 35953652, 2023). "It was reported that miR-3662, as a tumor suppressor of HCC, inhibited the Warburg effect and HCC growth by directly targeting HIF-1α and downregulating its expression, which regulated the expression of HIF-1α downstream target genes (GLUT1, HK2, PKM2, and LDHA)." (PMID 37274242, 2023). "Our strategy focused on the roles of HIF-1α and glycolysis, which may support the progression of canine GL, and the data showed the efficacy of EVO in inhibiting glycolysis processes and suppressing tumor growth both in vitro and in vivo." (PMID 38067241, 2023). "Nevertheless, it is important to note that the HIF-1α pathway may not directly induce tumor cell apoptosis, it does exert control over various factors that contribute to tumor progression." (PMID 37981704, 2023). "Besides HIF-1α silencing is sufficient to completely lose Multidrug Resistance 1 gene (MDR1) expression (the gene that guides the Multi-Drug Resistance, a critical challenge in BC) and to restore the chemo-sensitivity in tumour cells." (PMID 37407979, 2023).